OXSR1 (oxidative stress responsive kinase 1)
Diseases named in the same sentence as OXSR1 in open-access papers:
OXSR1 is named in the same sentence as 34 diseases in open-access papers, as found by Europe PMC text mining. Sharing a sentence is not in itself a finding about the gene and the disease. The quoted sentences say what the papers report.
Sepsis (7 papers, 2017 to 2025). Sepsis is defined as life-threatening organ dysfunction caused by a dysregulated host response to infection. "Curcumin-induced exosomal FTO from bone marrow stem cells alleviates sepsis-associated acute kidney injury by modulating the m6A methylation of OXSR1." (PMID 40989844, 2025). "In sepsis‐induced acute lung injury, OXSR1 overexpression promoted LPS‐induced inflammation and apoptosis in airway epithelial cells." (PMID 39739936, 2025). "And there was an inverse correlation between the expression of miR-93-5p and OXSR1 in the serums of patients with sepsis." (PMID 33468219, 2021). "Taken together, based on the functions of OXSR1 in apoptosis and inflammation, the effects of miR-191-5p on the improvement of sepsis-induced kidney injury might be mainly attributed to inhibiting the expression of OXSR1." (PMID 31362998, 2019). "Therefore, circ-FANCA functioned as a regulatory molecule in sepsis-engendered AKI via downregulating miR-93-5p and upregulating OXSR1." (PMID 33468219, 2021). "The different expression of miRNA might potentially be used to discriminate septic AKI from sepsis-non AKI and they were correlated with the regulation of mitochondrial oxidative stress and dysfunction, including PGC-1α, SIRT1, mTOR, OXSR1 and NOX5." (PMID 28296904, 2017).
breast carcinoma (4 papers, 2022 to 2024). "OXSR1 encodes a serine–threonine protein kinase, and studies have shown that high OSR1 expression causes an increase in deaths specifically attributed to breast cancer and is related to an increase in lymph node metastasis." (PMID 36414988, 2022). "Specifically, OXSR1 has been previously reported to mediate the TGF-β signaling pathway in breast cancer, promoting epithelial-mesenchymal transition (EMT) and metastasis through the phosphorylation of Smad2/3, EXOSC10 is a novel candidate factor that had not been identified before." (PMID 39619656, 2024).
endometritis (4 papers, 2023 to 2025). An acute or chronic, usually bacterial infectious process affecting the endometrium. "TLR4, IL-8, IL-17, NFKB, SLCA11A1, NCF4, Keap1, HMOX1, OXSR1, ST1P1, and SERP1 were manifestly expressed at much higher levels in the buffaloes with endometritis." (PMID 39195794, 2024). "The buffaloes with endometritis had considerably higher expression levels of TLR4, IL-8, IL-17, NFKB, SLCA11A1, NCF4, Keap1, HMOX1, OXSR1, ST1P1, and SERP1." (PMID 39195794, 2024). "Our findings showed that the buffaloes with endometritis had significantly higher TLR4, IL-8, IL-17, NFKB, SLCA11A1, NCF4, Keap1, HMOX1, OXSR1, ST1P1, and SERP1 expression levels." (PMID 39195794, 2024). "The expression levels of the genes TLR4, TLR7, TNF-α, NCF4, LITAF, OXSR1, TKT, RPIA, and AMPD1 were significantly greater in endometritis-affected Holstein dairy cows than in resistant ones." (PMID 37368756, 2023). "Gene expression levels were considerably higher in endometritis-affected cows than in resistant ones for the genes TLR4, TLR7, TNF-α, NCF4, LITAF, OXSR1, TKT, RPIA, and AMPD1." (PMID 37368756, 2023). "Nucleotide sequence variations between healthy and endometritis-affected cows were revealed using PCR-DNA sequencing for immune (TLR4, TLR7, TNF-α, IL10, NCF4, and LITAF), antioxidant (ATOX1, GST, and OXSR1), and erythritol-related (TKT, RPIA, and AMPD1) genes were reported by44." (PMID 38459095, 2024). "The following genes were assessed for their expression levels using real-time PCR in both the normal and endometritis-affected buffaloes: immune (TLR4, IL-8, IL-17, NFKB, SLCA11A1, and NCF4) and antioxidant (SOD, CAT, NDUFS6, Nrf2, Keap1, PRDX2, HMOX1, OXSR1, ST1P1, and SERP1)." (PMID 39195794, 2024). "Single nucleotide variants (SNPs) in the genes were discovered using PCR-DNA sequencing for immune (TLR4, TLR7, TNF-α, IL10, NCF4, and LITAF), antioxidant (ATOX1, GST, and OXSR1), and erythritol-related (TKT, RPIA, and AMPD1) genes found in resistant and endometritis-infected Holstein dairy cows." (PMID 37368756, 2023). "Molecular genetic analyses of the immunological (TLR4, TLR7, TNF-α, IL10, NCF4, and LITAF), antioxidant (ATOX1, GST, and OXSR1), and erythritol-related (TKT, RPIA, and AMPD1) genes comparing healthy and endometritis cows found differences in nucleotide sequence and transcript levels." (PMID 37368756, 2023). "The immune (TLR4, TLR7, TNF-α, IL10, NCF4, and LITAF), antioxidant (ATOX1, GST, and OXSR1), and erythritol-related (TKT, RPIA, and AMPD1) genes in endometritis-affected and healthy Holstein dairy cows were characterized in this research using a PCR-DNA sequencing technique." (PMID 37368756, 2023). "Nucleotide sequence variations between healthy and endometritis-affected cows were revealed using PCR-DNA sequencing for immune (TLR4, TLR7, TNF-α, IL10, NCF4, and LITAF), antioxidant (ATOX1, GST, and OXSR1), and erythritol-related (TKT, RPIA, and AMPD1) genes." (PMID 37368756, 2023).
Hypertension (4 papers, 2016 to 2023). The presence of chronic increased pressure in the systemic arterial system. "Because SPAK/OXSR1-modulated K+ channels also shuttle Cl−, Na2+, and Ca2+, this pathway has been studied for its role in hypertension." (PMID 35545295, 2022). "The small molecule, Compound B, reduces hypertension in animal models by inhibiting WNK phosphorylation of SPAK/OXSR1, preventing SPAK/OXSR1 activation." (PMID 35545295, 2022).
oral cancer (4 papers, 2021 to 2024). "The natural carotenoid lutein has been shown to reduce OXSR1 expression in oral cancer squamous cells." (PMID 35887124, 2022). "Our results, that have shown a significant increase of OXSR1 levels in both lutein and lutein Nps-treated oral cancer cells, may lead to the idea that, in our study conditions, this carotenoid revealed protective effects, probably via a molecular pathway resulting in OXSR1 enhancement." (PMID 34072756, 2021). "In contrast, oral cancer patients demonstrated elevated concentrations of key markers, including CPT1A, IL-6, OXSR1, and TNF-α, reflecting substantial alterations in metabolic and inflammatory pathways." (PMID 39456670, 2024). "Our findings highlight the crucial role of the oral microbiome in regulating key metabolic enzymes, such as CPT1A and OXSR1, as well as cytokines like TNF-α and IL-6 in oral cancer." (PMID 39456670, 2024). "Oral cancer tissues showed significantly elevated levels of the CPT1A protein; an increased presence of T-helper cell counts (CD4+); and higher levels of OXSR1, IL-6, and TNF-α." (PMID 39456670, 2024). "Additionally, increased levels of inflammatory and stress-related markers, including IL-6, oxidative-stress-responsive kinase 1 (OXSR1), and TNF-α, were observed in patients with oral cancer compared to healthy controls." (PMID 39456639, 2024).
schizophrenia (4 papers, 2011 to 2021). A major psychotic disorder characterized by abnormalities in the perception or expression of reality. "Interestingly, KCC2 and NKCC1 transcript levels were not altered in subjects with schizophrenia; however, transcripts for two kinases (OXSR1 and WNK3) that strongly regulate KCC2 and NKCC1 activity in opposite directions, are overexpressed in schizophrenia." (PMID 21904685, 2011). "However, they found overexpression of OXSR1 and WNK3 transcripts in schizophrenia." (PMID 35069119, 2021). "Previous studies found that messenger RNA (mRNA) expression levels of "Oxidative Stress Response kinase" (OXSR1) and "With No lysine Kinase 3" (WNK3) were increased in schizophrenia in the DLPFC." (PMID 25826365, 2015).
glioma (3 papers, 2014 to 2023). A benign or malignant brain and spinal cord tumor that arises from glial cells (astrocytes, oligodendrocytes, ependymal cells). "Expression of NKCC1 and its upstream kinases With-No-K (Lysine) kinase 1 (WNK1) and oxidative stress-responsive kinase-1 (OSR1) in different human glioma cell lines and glioma specimens were detected by western blotting and immunostaining." (PMID 24555568, 2014). "We previously found that TMZ stimulated NKCC1 protein upregulation and activation in human primary glioma cells (GC#99 and GC#22) through With-No-K (lysine) kinase 1 (WNK1) and oxidative stress-responsive kinase 1 (OSR1) signaling pathway." (PMID 32848856, 2020).
asthma (2 papers, 2022 to 2024). "We have newly discovered that variants of the OXSR1 gene, which is involved in the regulation of salt and cell volume, immune response, and oxidative stress, may affect asthma exacerbation." (PMID 34983467, 2022). "The common allele of rs1384006 C > T of OXSR1 was associated with the asthma exacerbation rate and a higher risk of being a frequent exacerbator, indicating that non-smoking asthmatics who carry common alleles may be vulnerable to asthma exacerbations." (PMID 34983467, 2022). "Second, there is still little information about the function of the OXSR1 gene in asthma." (PMID 34983467, 2022). "We aimed to determine whether genetic variants of Oxidative Stress Responsive Kinase 1 (OXSR1), a gene with functions of salt transport, immune response, and oxidative stress, are associated with exacerbation of asthma." (PMID 34983467, 2022). "The functional significance of Oxsr1 has not been previously explored in skeletal muscle or in aging, but single nucleotide polymorphisms of Oxsr1 were associated with exacerbation of the risk of asthma and altered smooth muscle cell function." (PMID 39223708, 2024). "Third, we could not confirm the causal relationship between the common allele variant of rs1384006 in the OXSR1 gene and asthma exacerbations in this study because we had no replication data using other independent cohort subjects." (PMID 34983467, 2022). "However, the relationship between OXSR1, a gene related to oxidative stress, and asthma exacerbation has never been studied." (PMID 34983467, 2022).
hepatocellular carcinoma (2 papers, 2020 to 2021). A malignant tumor that arises from hepatocytes. "Inhibition of WNK1 or its downstream kinases OSR1 (oxidative stress responsive kinase 1)/SPAK (Ste20-related proline alanine rich kinase) using chemical inhibitors decreased ectopic vessel formation as well as proliferation of xenotransplanted hepatoma cells." (PMID 32131390, 2020). "OXSR1 was unraveled to be abnormally upregulated in hepatocellular carcinoma (HCC) and its increase predicted poor prognosis and promoted HCC tumorigenesis." (PMID 33468219, 2021).
colon cancer (1 paper, 2024). "Certain oral bacteria, such as Porphyromonas gingivalis, are potential cancer-causing agents that induce oxidative stress via oxidative stress-responsive kinase 1 (OXSR1) and DNA damage, whereas other bacteria, such as Lactobacillus, act as antioxidants that potentially suppress colon cancer." (PMID 39456670, 2024).
endometrial cancer (1 paper, 2022). Primary or metastatic malignant neoplasm involving the endometrium (mucous membrane that lines the endometrial cavity). "Based on CPTAC data, OXSR1 is not overexpressed in endometrial cancer compared to control tissue." (PMID 35887124, 2022).
epilepsy (1 paper, 2025). A brain disorder characterized by episodes of abnormally increased neuronal discharge resulting in transient episodes of sensory or motor neurological dysfunction, or psychic dysfunction. "OXSR1 had pro‐oxidant and pro‐apoptosis in neurons to aggravate epilepsy progression." (PMID 39739936, 2025).
Hydrocephalus (1 paper, 2023). Hydrocephalus is an active distension of the ventricular system of the brain resulting from inadequate passage of CSF from its point of production within the cerebral ventricles to its point of absorption into the systemic circulation. "SPAK (Ste20-related proline-alanine-rich kinase)/OSR1 (oxidative stress-responsive kinase-1) are essential for regulating NKCC1 protein and are associated with NKCC1 protein activation in the lipopolysaccharides (LPS)-induced hydrocephalus." (PMID 38107410, 2023).
leukaemia (1 paper, 2025). "Targeting OXSR1 strongly suppressed the growth of MA9 leukaemia cells, in which the expression of STK39 is undetectable." (PMID 40425534, 2025). "We show that genetic depletion and pharmacological inhibition of WNK1 or its downstream phosphorylation targets OXSR1 and STK39 strongly reduce cell proliferation and induce apoptosis in leukaemia cells in vitro and in vivo." (PMID 40425534, 2025). "In mouse MA9 leukaemia cells, ectopic expression of an sgRNA-non-targetable wild-type human OXSR1 rescued the reduced proliferation phenotype observed by the disruption of endogenous OXSR1." (PMID 40425534, 2025).
liver cancer (1 paper, 2021). An epithelial or non-epithelial malignant neoplasm that arises from the liver. "Then, we also explored the correlation between the expression of 11 ROS-related genes and TNM stages in liver cancer, and the findings showed that the expression of CDKN2D, G6PD, MSRA, OXSR1, PFKP, and STK25 was connected with TNM stages (P < 0.05)." (PMID 34795841, 2021).
mastitis (1 paper, 2025). Inflammation of breast tissue during lactation or postpartum due to an obstructed duct or infection. "Levels of IFN-γ, IL-4, TNF-α, MYD88, CCL5, TLR4, TLR9, LTF, PRLR, Keap1 and OXSR1 genes expression were significantly up-regulated in ewes affected with mastitis than resistant ones." (PMID 40542007, 2025). "In the current investigation, qRT-PCR was used to measure the levels of antioxidant (CAT, GPX1, Keap1, OXSR1, ATOX1, GST, and Nrf2) and immune (IFN-γ, IL-4, TNF-α, MYD88, CCL5, TLR4, TLR9, LTF, and PRLR) genes in Barki ewes that were resistant and non-resistant to mastitis." (PMID 40542007, 2025).
retinoblastoma (1 paper, 2018). A malignant tumor that originates in the nuclear layer of the retina. "However, OXSR1 was identified to be overexpressed over two-fold in our proteomics study on retinoblastoma (unpublished data)." (PMID 29914080, 2018). "The substrates of WNK1 such as MAPK1, OXSR1, STK39 (SPAK), and ANKS1A were identified to be phosphorylated in our study, but their phosphorylation status was unchanged in retinoblastoma compared to control retina tissues." (PMID 29914080, 2018).
cancer (5 papers, 2011 to 2025). A tumor composed of atypical neoplastic, often pleomorphic cells that invade other tissues. "Oxidative stress responsive kinase 1 (OXSR1) was closely related to malignant progression of malignant tumors." (PMID 38155974, 2023). "Of these kinases, MAP2K1, OXSR1 and EPHA3 are implicated in cancer." (PMID 22219723, 2011).
tumor (3 papers, 2014 to 2022). "Moreover, it has been noticed that OXSR1 is a main actor in molecular pathways associated with anti-tumoural protection mechanisms." (PMID 34072756, 2021). "In our analysis eight new candidate tumor suppressor genes were identified, OXSR1 (3p22.2), BSG(19p13.3), NT5E(6q14.3), PLEKHG7(12q22), CMTM8(3p22.3), NETO2(16q12.1), ODZ3(4q35.1) and ERBB4(2q34)." (PMID 25551557, 2014). "MMP, OXSR-1, TAC, FOXO-3 and MMP-9 were measured in tumour cell lysates by the ELISA technique." (PMID 34072756, 2021). "Consequently, OXSR1-mediated activation of RELT should be considered an important mechanism for the apoptosis induction and tumour development inhibition." (PMID 34072756, 2021). "Besides the known tumor suppressor genes DOCK5 and PTEN, genes OXSR1, BSG, NT5E, PLEKHG7,CMTM8, NETO2, ODZ3, and ERBB4 adhered to our criteria and were qualified as novel candidate tumor suppressor genes." (PMID 25551557, 2014). "Recent studies have revealed that the dysregulation of WNKs contributes to tumor growth, metastasis, and angiogenesis through complex mechanisms, especially through phosphorylating kinase substrates SPS1-related proline/alanine-rich kinase (SPAK) and oxidative stress-responsive kinase 1 (OSR1)." (PMID 36123332, 2022).
infection (1 paper, 2022). The state of being infected such as from the introduction of a foreign agent such as serum, vaccine, antigenic substance or organism. "Our data expand this literature by showing depletion or inhibition of infection-induced OXSR1 increases host immunity to mycobacterial infection." (PMID 35545295, 2022). "To determine if SPAK and OXSR1 are involved in immunity, we infected zebrafish embryos with Mycobacterium marinum and analysed gene expression at 3 days post infection (dpi)." (PMID 35545295, 2022). "The results from the THP-1-derived macrophages confirm that the role of OXSR1 in the host response to infection is conserved across species." (PMID 35545295, 2022). "It is also likely that OXSR1 interacts with intracellular infections independently of NLRP3 inflammasome, potentially through the direct control of intracellular and vacuolar ion concentrations." (PMID 35545295, 2022). "Together, these results suggest that OXSR1 knockdown increases K+ efflux during infection." (PMID 35545295, 2022). "Here we sought to investigate whether the SPAK/OXSR1 pathway is involved in the host response to mycobacterial infection, and if this pathway could be manipulated as a host-directed therapy against infection." (PMID 35545295, 2022). "Infection-induced OXSR1 may suppress protective NLRP3 inflammasome responses and downstream IL-1β/TNF-α production." (PMID 35545295, 2022). "We showed that infection with WT M. marinum decreased the K+ content of OXSR1 knockdown cells but did not significantly affect the K+ content of WT cells." (PMID 35545295, 2022). "This suggests that OXSR1 inhibition may be an effective host-directed therapy strategy that induces beneficial inflammation at sites of infection without inducing detrimental systemic inflammation." (PMID 35545295, 2022). "In our infection model we found that WT, but not avirulent ∆ESX1, M. marinum induced expression of both OXSR1 and SPAK." (PMID 35545295, 2022).
respiratory diseases (1 paper, 2022). "OXSR1 has rarely been studied with regard to respiratory diseases, although it plays a role as a salt transportation, and cell volume control through ionic mechanisms and ion transport by bronchial epithelial cells is essential for healthy airways." (PMID 34983467, 2022).
OXSR1 also shares sentences with these, for which no sentence is quoted: acute kidney injury (4 papers); pseudohypoaldosteronism type 2 (2); glioblastoma (1); gout (1); Hyperkalemia (1); inflammatory bowel disease (1); Intellectual disability (1); kidney injury (1); lung (1); lung squamous cell carcinoma (1); lymph node metastasis (1); Obesity (1); osteosarcoma (1).